ENSG00000257390 (novel protein)
Gene: Protein-coding gene on chromosome 12 (55,757,275 to 55,827,546, reverse strand). Ensembl gene ENSG00000257390.
Genetic constraint (gnomAD): Loss-of-function variants: 7 observed, 44.68 expected, observed/expected ratio (o/e) 0.16, 90% interval 0.088 to 0.29. Missense variants: 341 observed, 482.37 expected, observed/expected ratio (o/e) 0.71, 90% interval 0.65 to 0.77. Synonymous variants: 163 observed, 166.1 expected, observed/expected ratio (o/e) 0.98, 90% interval 0.86 to 1.12.